ENSG00000212363
Synonyms: LOC124900209
Gene: Small nucleolar RNA gene on chromosome 5 (74,882,656 to 74,882,783, reverse strand). Ensembl gene ENSG00000212363.
Gene Ontology:
Biological process: RNA processing
Cellular component: nucleolus
Homologues: Paralogues in human: SNORA40B (92% identical), SNORA40 (89% identical), SNORA40C (87% identical).